IL10 (interleukin 10)
Diseases named in the same sentence as IL10 in open-access papers (continued):
Sharing a sentence is not in itself a finding about the gene and the disease.
tumor (continued). "The secretion of IL-8, IL-10 and TGF-β acts on NK cells and tumor cells and induces MICA/B shedding, the downregulation of MHC-Class I and the impairment of NK cell activity." (PMID 34445750, 2021). "Meanwhile, IL-10, TGF-β, TLR4, MYD88 and NF-κB in tumor tissue were increased, indicating that the LC model of mouse was successfully developed." (PMID 33967748, 2021). "STAT3-activating cytokines (e.g., IL6, IL10, VEGF) secreted by tumor cells promote abnormal dendritic cell differentiation and globally suppress dendritic cell maturation and activation." (PMID 34944848, 2021). "In contrast, M2-macrophages secrete anti-inflammatory cytokines such as IL-10, TGF-β and others to prevent T cells from effectively exerting their anti-tumor functions." (PMID 34638420, 2021). "Atovaquone (ATQ) reduces the expression of RPS19, MDSCs, Tregs and immunosuppressive cytokines IL-10 and TGF-β in tumor cells." (PMID 34068008, 2021). "Regulation T cells (Tregs) help tumor cells escape from attacks of immune system by releasing immunosuppressive cytokines, such as IL-10 and TGF-β1, and the expression of tumor-infiltrating Tregs has a close relationship with the prognosis of cancer." (PMID 34616851, 2021). "IL-10 expression was higher in the tumor cells from the HET/Eμ-TCL1A mice and even higher in the ROKO/Eμ-TCL1A mice than in WT/Eμ-TCL1A mice, suggesting that PTPROt decreases enhanced IL-10 expression." (PMID 34206047, 2021). "It was shown, that circulating monocytes or tissue residing macrophages are recruited and stimulated by different tumor-derived signals, such as chemo-attractants, e.g. CCL2 or cytokines, e.g. IL-4, IL-10 and IL-13." (PMID 34579743, 2021). "Specific to breast cancer, ovarian cancer, colorectal cancer, cervical cancer and prostate cancer, Bregs exert immunosuppressive function by secreting IL-10 and TGF-β to promote tumor development." (PMID 34235074, 2021). "The analysis of tumor tissues from 104 NSCLC patients with HPD revealed a large number of M2-type PD-L1+ macrophages, which secrete IL-10 to mediate the occurrence of HPD through the depletion of the PD-1 antibody." (PMID 34290608, 2021). "IL-10 and TGFβ have the potentiality to convert CD4+T cells into Tregs that further would help tumor progression." (PMID 34485117, 2021). "IL-10 production in liposomal plus CpG-ODN group was lower than peptide plus CpG-ODN and liposomal groups (P < 0.01 and P < 0.05 respectively) in tumor site." (PMID 34282215, 2021). "We also tested the impact of CXCL1/IL10/CCL4 on the colony forming ability of PC cells; this in vitro technique examines the capability of tumour cells to form large colonies." (PMID 34359731, 2021). "Treg suppresses the pernicious effect of CTLs by secreting IL-10 and TGF-β, thus realizing tumor immune escape." (PMID 34539408, 2021). "Tao and his colleagues reported that effector B cells directly killed tumor cells via the Fas/FasL and CXCR4/CXCL12 pathways, and the killing activities can be improved by IL-2 and inhibited by IL-10." (PMID 34118931, 2021). "In clinical studies, the immunosuppressive function of IL-10 in tissue and serum of PDAC patients possesses a clear positive correlation with tumor stage and poor differentiation status." (PMID 34066839, 2021). "TAMs can recognize dying tumor cells through the MER tyrosine-protein kinase (MERTK) receptor and upregulate the expression of wound-healing factors such as TGF-β, IL-10, and ARG1 that suppress anti-tumor immunity." (PMID 34603327, 2021). "Tumour cells can secrete regulatory cytokines such as transforming growth factor beta (TGF-β) and interleukin-10 (IL-10) that reduce the activation of NK cells." (PMID 34831327, 2021). "This is not only due to the overexpression of M2-type polarizing signals (such as IL-10, IL-4, IL-13, and TGF-β) in the TME, but is also related to the fact that pro-inflammatory cytokines can also confer pro-tumor properties to TAMs." (PMID 34178692, 2021).
tumor (continued). "In a breast cancer mouse model, delivery of this miRNA mimic led to a reversal of the tumor-suppressive properties of TAMs by acting as a TLR-7 agonist and suppressing IL-10 production, thereby inhibiting tumor growth." (PMID 33530393, 2021). "Yang and Lattime found that IL-10-expressing UBC cell line MB4 suppressed the ability of dendritic cells (DCs) to stimulate CD4+ and CD8+ T cell anti-tumor responses." (PMID 34541363, 2021). "Bregs were shown to produce high levels of IL-10 and TGF-β which can downmodulate tumor-specific T cell- and NK cell-mediated responses, while increasing the frequency of Tregs in the TME." (PMID 34072260, 2021). "Each CD44+ cell-type functions immunosuppression through different ways: CD44+ tumor cells express CD276, IL13, VEGFA, and IDO1; CD44+ TAMs express IL10, TGFB1, VEGFA, and HAVCR2; CD44+ T cells express CD274, TGFB1, CTLA4, LAG3, and PDCD1." (PMID 35187044, 2021). "Tumor cells can induce B cells to secrete to IL-10 through multiple mechanisms including CD40L signals and tumor-derived exosomes." (PMID 33995344, 2021). "IL-10 and TGF- β 1 has been shown to promote tumor cell immune escape by inhibiting T cell proliferation." (PMID 34267752, 2021). "After 24-h co-incubation of tumor cells and effector T cells at an E:T ratio of 10:1, B7-H3 CAR-T cells produced significantly higher amounts of IFN-γ, TNF-α, IL-2, IL-6, IL-4 and IL-10 in the culture supernatants compared with vehicle T cells." (PMID 33514401, 2021). "Therefore, elevated levels of IL-10 may facilitate tumor immune escape." (PMID 34034721, 2021). "It not only secretes immunosuppressive cytokines like TGFβ and IL-10 but also expresses high-affinity IL-2 receptor CD25, which sequesters IL-2 from the tumor milieu." (PMID 34485117, 2021). "Significantly more IFN-γ-expressing CD8+T lymphocytes, elevated levels of IFN-γ and IL-2, fewer CD25+ forkhead box P3 (Foxp3) +Tregs and decreased levels of IL-10 and TGF-β were detected at tumor sites." (PMID 33435564, 2021). "IL-10 is regarded as a major immunosuppressive, pro-tumoral cytokine, and was highly upregulated in macrophages and CD8+ T cells in the tumor." (PMID 33918618, 2021). "In terms of polarization, TAMs that adopt an M2 phenotype within TME are shown to promote tumor survival through the secretion of the immunosuppressive cytokines, TGF-β, IL-4, and IL-10." (PMID 34483843, 2021). "Our data indicate that EMT-high tumors lack CTL cytotoxic activity and hence tumor clearance due to limited support of IFNγ, TNFα, and IL2 and abundance of suppressive IL10 and TGFβ cytokines." (PMID 35096592, 2021). "Several different tumor-related soluble molecules are involved in this form of immunosuppression: Vascular Endothelial Growth Factor (VEGF), Prostaglandin E2, TGF-β, IL-10, soluble phosphatidylserine, MICA Fas and FasL100." (PMID 33673332, 2021). "TGF-β/IL-10 genes, known to play critical roles in inhibiting CD8 and CD4 T cell functions and IL-2/IFNγ genes, which are known to boost the anti-tumor immune response." (PMID 34728682, 2021). "The impact of C-7 on the levels of various cytokines (IFNγ, TNF, IL-6, and IL-10) and the chemokine CXCL10 was assessed in 1-day co-culture supernatants of dissociated CRC tumor cells and autologous PBMC." (PMID 34771609, 2021). "Contrarily, M2 macrophages produce anti-inflammatory cytokines such as IL-10 and Tumor growth factor (TGF)-β, which promote tumor progression." (PMID 34072260, 2021). "Through secretion of immunosuppressive cytokines such as IL-10 and TGF-β, macrophages shut down the immune system by effectively inhibiting CD8+ T cells – the dominant anti-tumor T-cell type – and dendritic cell responses." (PMID 33649008, 2021). "Serum concentrations of tumor markers CEA and CA19-9 were reduced after treatment with probiotics, while the expression of interferon gamma (IFN-γ), interleukin-10(IL-10), and the count of CD4+ and CD8+ cells were upregulated upon intervention." (PMID 34992527, 2021).
tumor (continued). "Pro-tumorigenic TAMs produce an array of inhibitory molecules such as ARG1, IL-10, and IDO that exert immunosuppression functions, and angiogenesis factors, such as VEGF and TGF-β that promote tumor progression." (PMID 34988072, 2021). "The overexpression of B7-H4 promotes the proliferation of FOXP3+ regulatory T cells and the secretion of IL-10 and TGF-β1, inhibiting antigen presentation cell function and exerting immune tolerance in tumor microenvironments." (PMID 33937019, 2021). "IL-10 induces an immunosuppressive microenvironment in PDAC patients, reduces effector cell function and shifts toward Th2 cytokines, and therefore helps tumor cells to escape immune recognition." (PMID 34066839, 2021). "In addition, citCp450 stimulated IL-10 responses when delivered as part of the combination vaccine suggesting this response is not affected by the other epitopes in the combination vaccine but may result in an impaired anti-tumour response." (PMID 34858415, 2021). "We then examined the changes in M2-like TAM markers (CD163, CD206, CD209, IL-10 and Arginase 1) and M1-like TAM markers (CD80, CD86, IL-12, and TNFα) induced by CM from ILT4-downregulated tumor cells." (PMID 33537094, 2021). "TGF-β1 and IL-10 levels were reduced, while TNF-α and IFN-γ were increased in the tumor microenvironment in response to resveratrol treatment." (PMID 33802331, 2021). "Another important alteration in the leukemic TME is the increased levels of anti-inflammatory and immunosuppressive cytokines, such as IL-10 and TGF-β, and the high expression of PD-1 and TIGIT, which contribute to tumor progression and immune evasion." (PMID 34867958, 2021). "It is described that the pathway leads to IL-10 and galectin-1 production, resulting in an increase of matrix-metalloproteases 2 and 9 (MMP-9/MMP-2), finally enhancing tumor migration." (PMID 34572948, 2021). "While baseline IFNg is higher in the recurrent tumor, the level of TNFa, RANTES (CCL5), IP-10, IL-5, IL-10, MIP1a (CCL3), MIP1b (CCL4), and GM-CSF are all significantly lower in the recurrent tumor." (PMID 34221953, 2021). "In SMMC-7721-tumor-bearing mice, Tf-LP-ERN treatment increased the serum concentration of TNF-α (P < 0.01) and decreased the serum concentrations of IL-10 (P < 0.05) and CCL11 (P < 0.05)." (PMID 34513705, 2021). "T-reg cells that also release TFG-β and IL10 will further suppress the activation of CD8 T cells, promoting tumor cell growth." (PMID 34447383, 2021). "Treg cells are involved in tumor progression by explicitly improving the expression of CTLA4; glucocorticoid-induced TNF receptor (GITR); IL-2, IL-10 and IL-35; lymphocyte-activation gene-3 (LAG3); and TGF-β." (PMID 34834282, 2021). "In order to mimic an immunosuppressive environment, we assessed the functionality of our BiMAb in co-cultures of tumor cells with CD3+ T cells and titrated amounts of exogenous IL-10 and TGF-β." (PMID 34484225, 2021). "A study by Lee and colleagues suggested that IL-10 inhibits the IL-6/STAT3 axis on MDSCs and weaken tumour progression." (PMID 34336101, 2021). "Blocking IL10 abrogates the SPON2-mediated intratumoral M2-TAM enrichment into the tumor and tumor growth." (PMID 34583750, 2021). "In fact, macrophages produce proinflammatory cytokines, such as TGF-β, IL-6, IL-10, and TNF-α, that induce stem cell-like characteristics in tumor cells, thereby sustaining these tumor cells and allowing them to continue to grow." (PMID 34502312, 2021). "Many immunosuppressive factors produced by MDSCs, such as TGF-β, VEGF, IL-10, and IL-6, have been shown to induce EMT and stemness in various tumor cells." (PMID 35004667, 2021). "Orthotopic HCC mice treated with these DCs harbored an elevated number of T lymphocytes, increased levels of IFNγ and decreased levels of IL-10 and TGF-β at tumor sites." (PMID 33435564, 2021).
tumor (continued). "Macrophages are per se able to present antigens on MHC molecules, but in the tumour environment, MDSCs lead to a down-regulation of MHC II on the TAMs via IL-10." (PMID 34445385, 2021). "In the TME, immunosuppressive cytokines such as IL-10 and TGF-β secreted by MDSCs are important factors that inhibit the anti-tumor immune response and promote tumor progression." (PMID 34447750, 2021). "TAM generates many immunosuppressive factors and chemokines, including IL-6, IL-10, TNF-α, TGF-β, etc., which decrease antigen presentation and impair T cell activity, allowing tumor cells to elude the body’s immunological surveillance." (PMID 34922542, 2021). "Tregs then expand and proliferate in response to tumor-derived factors (TGF-β, adenosine, VEGF, and IL-10) within the TME." (PMID 34025641, 2021). "Our results confirmed the notion that disrupting tumor hypoxia is beneficial for ICB mediated immunotherapy, as exemplified with reduced MDSCs, M2 TAMs, Treg, TGF‐β, and IL‐10 and strengthened CTLs and Tem." (PMID 34085419, 2021). "When exposed to IL4, IL5, IL10, IL13, CSF1, TFGB1, and prostaglandin E2 (PGE2), it transitions from a pro-inflammatory state to an anti-inflammatory and pro-tumor state, that is, to an M2-like state." (PMID 34447750, 2021). "TEMs are highly angiogenic and lymphangiogenic cells that display immune-suppressive activity by secreting IL-10 and VEGF in large amounts and dampen in vitro, tumor-specific T-cell proliferation by tumor dendritic cells." (PMID 34209703, 2021). "Mechanically, OK-432 inhibited the expression of IL-10 and promoted the expression of TNF-α in TAMs, resulting in enhanced anti-tumor capability." (PMID 34541363, 2021). "In a tumor microenvironment, hypoxia-induced release of HMGB1 induces the accumulation of anti-inflammatory M2-like (“alternatively activated”) macrophages and IL-10 production by RAGE signaling, thereby favoring tumor development." (PMID 34685561, 2021). "The pro-inflammatory cytokines (TNF-α, IL-12, IFN-γ and IL-2) increased in the spleen of tumour-bearing mice that had been treated with VES, whereas the anti-inflammatory cytokine IL-10 decreased transcriptionally." (PMID 34093795, 2021). "Compared to healthy individuals, the NPC patients exhibited elevated levels of IL-1β, IL-2 and IL-10, which is in accordance with previous findings in patients with NPC and in tumor-bearing rodent models." (PMID 34900691, 2021). "Treatment with APS inhibited tumor development in MDSCs by reducing the proportion of Gr-1+CD11b+MDSCs and limiting vascular endothelial growth factor (VEGF) and IL-10 expression." (PMID 34721026, 2021). "Upon accumulation in the tumor site, these tumor-suppressive TAMs drive immune suppression and angiogenesis through anti-inflammatory factors such as arginase (Arg1), TGF-β, IL-10, and VEGF." (PMID 34359588, 2021). "In a skin carcinogenesis model, VEGF-A expression on tumor cells with IL10 and IL4 secreted by tumor cells and macrophages, respectively, induced M2 polarization that promoted tumor growth." (PMID 34447383, 2021). "Once within the tumor, growth factors expressed by the tumor (M-CSF, IL-34, TGF-b, and IL-10) induce an immunosuppressive macrophage phenotype (M2 macrophages)." (PMID 33917061, 2021). "Anti-inflammatory M2 macrophages are considered protumorigenic as they express immunosuppressive molecules such as IL-10, programmed death-ligand 1 (PD-L1), and transforming growth factor (TGF)-β—favoring tumor growth." (PMID 34066392, 2021). "The expression of M1 macrophage markers iNOS, IL-1β, TNF-α and CD86 was increased, and the expression of M2 macrophage markers IL-10, Arg-1 and CD206 was reduced in the tumour tissues of tumour-bearing mice." (PMID 34726570, 2021). "Secretion of immunosuppressive cytokines such as IL-10 and TGF-β by tumor cells and regulatory T cells result in the suppression of CD8 T cell-mediated tumor killing, due to the suppression of IFN-γ from T cells." (PMID 34960142, 2021).
tumor (continued). "As mentioned in previous sections, the metabolic microenvironment of the tumor is different with the high supplement of TGF-β1 and IL-10." (PMID 33532902, 2021). "TAMs in MM also appear to have increased IL-6 and IL-10 expression, along with decreased IL-12 and TNF-α expression, leading to tumor growth and immune suppression." (PMID 33717170, 2021). "We observed that ILT4 knockdown in tumor cells decreased M2-like markers, including CD163, CD206, IL-10, and Arginase 1 but increased M1-like markers including CD80, CD86, IL-12, and TNFαin TAMs." (PMID 33537094, 2021). "Neutrophils which exist in tumor microenvironment are capable of producing angiogenic chemokines and cytokines including CCL2,CCL3, CCL5, CCL10, IL4 and IL10 to promote tumor growth, invasion and angiogenesis." (PMID 34123808, 2021). "M1 cells can stimulate antitumoral immune responses by releasing TNF-α and nitric oxide; however, M2 cells can express VEGF, IL-10, TGF-β, and indoleamine 2,3-dioxygenase (IDO), leading to tumor development." (PMID 34947886, 2021). "This led to a reduction in collagen, BCAF secreted immune suppressive cytokines such as IL-6 and IL-10, and an increase in T cells (CD8+ and CD4+) in the tumor." (PMID 34944738, 2021). "FRβ was expressed on IL-10-producing M2-like macrophages (CD163+, CD68+, CD14+ IL-10), corresponding to the anti-inflammatory/pro-tumor TAM subtype." (PMID 35008360, 2021). "TAMs are activated by IL-10 and TGF-β, secrete high levels of cytokines that decrease the activation of T cells, and participate in tumor progression and the formation of metastases." (PMID 34204474, 2021). "These functions support a tumor-suppressive role for B cells; however, immunosuppressive regulatory B cells that produce TGF-β and IL-10, promoting the same effects as Treg cells, have also been found." (PMID 33494389, 2021). "In breast cancer, DCs purified from cancer patients have a decreased ability to stimulate T cells, and tumor-infiltrating DCs suppress the function of CD8+ T cells via TGF-β, NO, IL-10, VEGF, and arginase I." (PMID 34204474, 2021). "After radiotherapy, altered inflammatory cytokines (such as IL-6, IL-10, and TNF) lead to the recruitment of TAMs with a tissue reparative phenotype and contribute to tumor recurrence and metastasis." (PMID 34733785, 2021). "IL-10 is secreted by immune cells as well as by GBM cells and enhances tumour growth, inhibits the production of interferon-γ (IFN-γ) and tumour necrosis factor-α (TNF-α) by the immune system, and suppresses the antigen presentation process." (PMID 33804731, 2021). "Tumor cells that are known to produce a variety of immunosuppressive factors such as PGE2, ADO, IL-10, and TGF-β, appear to play a major role in the conversion of CD4+CD25neg precursors to CD4+CD25+CD39+FOXP3+ Treg." (PMID 34442398, 2021). "These cSCC CD69+/CD103+ TRMs exhibited increased IL-10 production, and higher CD39, CTLA-4 and PD-1 expression compared with CD103− TRMs in the tumor." (PMID 33479027, 2021). "T cell receptor (TCR) interaction with IL-10 and TGF-β signaling facilitates the infiltration of Tregs into the tumor microenvironment by regulating the CCL6/CCL20 axis." (PMID 34947886, 2021). "In our study, we used a 3-color Fluorospot assay allowing analyses of tumor-specific IFN-y, IL-5 and IL-10 producing lymphocytes." (PMID 33006650, 2021). "During tumor progression TAMs often switch to an anti-inflammatory M2 status after exposure to cytokines within the TME including: IL-4, M-CSF/CSF1, IL-10, IL-33, IL-21, and TGF-β." (PMID 35127700, 2021). "Macrophage colony-stimulating factor derived from Lewis lung carcinoma induced FASN expression in TAMs, stimulating tumor growth and angiogenesis in ARG1- and IL-10-dependent manner." (PMID 34742349, 2021). "Tumor-bearing mice treated with T-cells and BiTEDs showed significantly elevated levels of systemic IL-2, IFN-γ, TNF-α, and IL-10, seven days after treatment." (PMID 33936101, 2021).